RPL39 (ribosomal protein L39)
Description:
RNA-binding component of the large ribosomal subunit. The ribosome is a large ribonucleoprotein complex responsible for the synthesis of proteins in the cell.
Synonyms: L39; eL39; RPL39P42; RPL39_23_1806
Tractability: Small molecule: an approved drug acts on it; a structure with a bound ligand is known; a high-quality ligand is known. PROTAC: ubiquitination databases record sites on it; a small molecule that binds it is known. Other modalities: a drug acting on it is in phase 2 or 3 trials.
Gene: Protein-coding gene on chromosome X (119,786,497 to 119,791,662, reverse strand). Ensembl gene ENSG00000198918.
Subcellular location: Cytoplasm
Pathways (Reactome):
Metabolism of proteins: Eukaryotic Translation Termination; Formation of a pool of free 40S subunits; GTP hydrolysis and joining of the 60S ribosomal subunit; L13a-mediated translational silencing of Ceruloplasmin expression; PELO:HBS1L and ABCE1 dissociate a ribosome on a non-stop mRNA; Peptide chain elongation; Ribosome Quality Control (RQC) complex extracts and degrades nascent peptide; SRP-dependent cotranslational protein targeting to membrane; ZNF598 and the Ribosome-associated Quality Trigger (RQT) complex dissociate a ribosome stalled on a no-go mRNA
Metabolism of RNA: Major pathway of rRNA processing in the nucleolus and cytosol; Nonsense Mediated Decay (NMD) enhanced by the Exon Junction Complex (EJC); Nonsense Mediated Decay (NMD) independent of the Exon Junction Complex (EJC)
Cellular responses to stimuli: Response of EIF2AK4 (GCN2) to amino acid deficiency
Developmental Biology: Regulation of expression of SLITs and ROBOs
Disease: Viral mRNA Translation
Metabolism: Selenocysteine synthesis
Gene Ontology:
Molecular function: structural constituent of ribosome; RNA binding
Biological process: antibacterial humoral response; antimicrobial humoral immune response mediated by antimicrobial peptide; cytoplasmic translation; defense response to Gram-positive bacterium; innate immune response in mucosa; negative regulation of myoblast fusion; striated muscle contraction; translation
Cellular component: cytoplasm; cytosolic large ribosomal subunit; cytosolic ribosome; extracellular region; cytosol; ribosome
Homologues: Orthologues: macaque RPL39 (100% identical), mouse Rpl39 (100% identical), pig RPL39 (100% identical), rabbit RPL39 (100% identical), rat Rpl39 (98% identical), zebrafish rpl39 (98% identical). Paralogues in human: RPL39L (92% identical).
Diseases named in the same sentence as RPL39 in open-access papers:
RPL39 is named in the same sentence as 20 diseases in open-access papers, as found by Europe PMC text mining. Sharing a sentence is not in itself a finding about the gene and the disease. The quoted sentences say what the papers report.
breast carcinoma (9 papers, 2018 to 2025). "Metaplastic breast cancer has a high ribosomal protein L39 (RPL39) A14V mutation (97.5%) associated with poor overall patient survival." (PMID 33435254, 2021). "The similar role of RPL39 in regulating cell proliferation has also been reported in placental trophoblast cells, breast cancer cells, glioma cells, and pancreatic cancer cells." (PMID 39957991, 2025). "RPL39, another protein found overexpressed in our study of AA-treated tissue, has been previously reported to be overexpressed in breast cancer." (PMID 37888706, 2023). "Knocking down RPL39 could significantly inhibit the occurrence of lung metastasis of breast cancer in immunodeficiency mouse models, and most breast cancer patients with lung metastasis have acquired mutations of RPL39." (PMID 36004921, 2022). "Although the function of RPL39 is unknown in breast cancer, N(G)-methyl-L-arginine acetate, a pan-iNOS inhibitor, decreased breast cancer cell proliferation in in vitro and in vivo mouse models." (PMID 33435254, 2021). "Mechanistically, RPL39 and MLF2 expression was associated with iNOS signaling, and their mutations were associated with shorter median time to relapse in a cohort of 53 breast cancer patients, which suggests that iNOS inhibition represents a promising strategy for the treatment of TNBC." (PMID 33138097, 2020). "Moreover, downregulation of RPS19 or RPL39 suppressed breast tumor growth and progression in a transgenic breast cancer model, or tumor initiation and lung metastasis in patient-derived and human breast cancer xenografts, respectively." (PMID 30425236, 2018). "Targeting RPL39 and MLF2 reduces tumor initiation and metastasis in breast cancer by inhibiting nitric oxide synthase signaling." (PMID 34497807, 2021). "A more interesting study identified two previously unidentified cancer genes, RPL39 and MLF2, by selective shRNA knockdown of genes from this tumorigenic signature, which impacted breast cancer stem cell self-renewal and lung metastases." (PMID 34497807, 2021).
pancreatic cancer (4 papers, 2021 to 2025). "RPL39 knockdown by siRNA in pancreatic cancer is also linked to cancer cell regression and apoptosis enhancement in vivo and in vitro." (PMID 34873618, 2021). "In pancreatic cancer, knockdown of RPL39 inhibited cell proliferation and enhanced cell apoptosis." (PMID 36248799, 2022). "Depletion of RPL39 suppressed the proliferation of pancreatic cancer." (PMID 35934718, 2022). "RPL39 is overexpressed in the most aggressive pancreatic cancer cell lines PANC-1 and MIA PaCa-2." (PMID 34873618, 2021). "The effect of RPL39 on pancreatic cancer cell apoptosis seems to be dependent on caspase 8 activation suggesting that targeting RPL39 could be a potential treatment in pancreatic cancer." (PMID 34873618, 2021).
glioma (3 papers, 2022 to 2025). A benign or malignant brain and spinal cord tumor that arises from glial cells (astrocytes, oligodendrocytes, ependymal cells). "Furthermore, the expression of RPL39 was significantly associated with the prognosis of glioma patients with different clinical features (IDH status and WHO grade)." (PMID 36248799, 2022). "First, the CCK8 test was performed to detect the viability of glioma cells, and the results showed that RPL39 knockdown significantly reduced the viability of U251 and U87 cells, while RPL39 overexpression increased cell viability." (PMID 36248799, 2022). "In conclusion, RPL39 was overexpressed in gliomas and positively correlated with tumour aggressiveness." (PMID 36248799, 2022). "In the TCGA database, we found that the expression level of RPL39 in glioma tissue was significantly higher than that in normal brain tissue." (PMID 36248799, 2022). "Knockdown of RPL39 in vitro significantly inhibited the proliferation and migration of glioma cells, whereas overexpression of RPL39 had the opposite effect." (PMID 36248799, 2022). "RPL39 has not been studied in glioma, and we further explored the function of RPL39 in glioma." (PMID 36248799, 2022). "Finally, RPL39, as one of the hub genes, was found to be closely related to the prognosis of glioma patients." (PMID 36248799, 2022). "In tumour research, disruption of the extracellular matrix is essential for tumour migration and invasion; therefore, we speculate that RPL39 may affect EMT progression in glioma cells." (PMID 36248799, 2022). "In conclusion, RPL39 could promote the proliferation of glioma cells." (PMID 36248799, 2022). "Next, the TCGA database was used to explore the effect of RPL39 on the survival of glioma patients, and the KM curve showed that the survival time of glioma patients with high RPL39 expression was significantly shorter than that of glioma patients with low RPL39 expression." (PMID 36248799, 2022). "RPL39 promoted the proliferation of glioma cells and changed the EMT status of glioma cells; these results were consistent with those of previous studies." (PMID 36248799, 2022). "RPL39 was shown to be highly expressed in IDH wild-type glioma patients, and its expression increased with glioma grade." (PMID 36248799, 2022).
ovarian carcinoma (3 papers, 2022 to 2025). A malignant neoplasm originating from the surface ovarian epithelium. "We analyzed the prognostic value of RPL39 in patients with ovarian cancer, and found that the overexpression of RPL39 protein in 1074 patients with EOC was associated with a shorter OS than that in the 361 of those with a lower AGK protein expression (HR = 1.31, Logrank P = 0.00034)." (PMID 35934718, 2022). "Tissue analysis of ovarian cancer patients confirmed that acylglycerol kinase promotes chemotherapy resistance in epithelial ovarian cancer through interaction with ribosomal protein L39." (PMID 40438494, 2025). "Ribosomal protein L39 sustains mitochondrial cristae morphogenesis and facilitates reactive oxygen species production in ovarian cancer." (PMID 38052785, 2023).
Infertility (1 paper, 2023). "Recent studies have suggested that RPL39 and its associated proteins that participate in ribosome biogenesis and protein synthesis may be correlated with human infertility." (PMID 38012716, 2023). "The topological analysis of the WGCN of the testis transcriptional cell atlas highlighted important somatic genes in this network, including RPL39, RPL10, RPL13A, FTH1, RPS2, and RPL18A, which have been reported to be associated with infertility." (PMID 38012716, 2023).
ischemic stroke (1 paper, 2019). A stroke disorder caused by obstruction of blood flow to the brain, due to thrombotic (local blood clot formation) or embolic (due to a blood clot or other material traveling from another site) event. "First of all, four proteins were involved in ribosome function during ischemic stroke, namely, RPL26, RPL17, RPL39, and RPS13." (PMID 31223330, 2019).
lung carcinoma (1 paper, 2022). "The expression of RPL39 was found to impact the capacity of self-renewal and drug resistance of breast CSC in lung cancer." (PMID 35934718, 2022).
male infertility (1 paper, 2023). The inability of the male to effect fertilization of an ovum after a specified period of unprotected intercourse. "We also identified key somatic cell genes, including RPL39, RPL10, RPL13A, FTH1, RPS2, and RPL18A, which were highly influential in the weighted gene co-expression network of the testis transcriptional cell atlas and have been previously implicated in male infertility." (PMID 38012716, 2023).
metaplastic breast carcinoma (1 paper, 2022). A group of invasive breast carcinomas characterized by the presence of an adenocarcinomatous component which is admixed with a dominant component that is composed of squamous cells, spindle cells, or mesenchymal cells. "In metaplastic breast cancer, patients with high expression of RPL39 had lower overall survival, and RPL39 increased cell proliferation and migration by inducing nitric oxide synthase (INO)-mediated NO production." (PMID 36248799, 2022).
preeclampsia (1 paper, 2023). Preeclampsia is a hypertensive disorder of pregnancy that is characterized by new-onset hypertension with proteinuria presenting after 20 weeks of gestation, and depending on mild or severe forms may initially present with severe headache, visual disturbances, and hyperreflexia. "Preeclampsia is also regulated by ribosomal protein L39 (RPL39), a ribosomal protein that belongs to the S39E family of ribosomal proteins." (PMID 37174083, 2023). "In preeclampsia, however, the opposite is true; RPL39 is down-regulated and CDH1 is up-regulated, which inhibits trophoblast invasiveness." (PMID 37174083, 2023).
triple-negative breast carcinoma (1 paper, 2023). An invasive breast carcinoma which is negative for expression of estrogen receptor (ER), progesterone receptor (PR), and human epidermal growth factor receptor 2 (HER2). "Knockdown of RPL39 in triple-negative breast cancer (TNBC) xenografts significantly inhibited primary tumor growth and metastasis." (PMID 37888706, 2023).
tumor (15 papers, 2015 to 2025). "Alteration of the expression of ribosomal proteins RPL10 and RPL39 has been linked to tumor initiation and BC progression." (PMID 37922300, 2023). "For example, upregulation of expression of ribosomal proteins uL6 (gene RPL9), eL15 (RPL15), and eL39 (RPL39) is associated with increased tumor growth and metastasis in some cancers." (PMID 33990576, 2021). "The tumor tissues with a high level of AGK staining revealed strong RPL39 signals." (PMID 35934718, 2022). "RPS19 induces the production of immunosuppressive cytokines and promotes tumor growth which can be impaired by the blockage of RPS19 while the knockdown of RPL39 in triple-negative breast cancer (TNBC) xenografts reduces significantly primary tumor growth, as well as metastasis." (PMID 34873618, 2021). "Increased expression of BUD31, RIP4, and RPL39 have been previously correlated with disease malignancy and associated worse overall survival in patients with GBM, with in vitro overexpression of RPL39 associated with enhanced proliferation and migration of tumor cells." (PMID 39766155, 2024). "Recent studies found that in these cancers, the expression and activity of ADAR1 can be regulated by tumor-promoting proteins CPSF6 (cleavage and polyadenylation factor-6) and mutant RPL39 (ribosomal protein L39, A14V)." (PMID 30619092, 2018). "We have recently described two novel cancer genes (RPL39 and MLF2) that are important for tumor initiation and metastasis and are regulated by the NO signaling pathway." (PMID 25849745, 2015). "Importantly, in addition to the aberrant reactivation of genes on the inactive X, aberrant silencing of several genes that normally escape XCI, such as RAB9A, BCOR, RPL39, or PNPLA4 was also observed in tumor cell lines." (PMID 25653311, 2015).
cancer (6 papers, 2015 to 2024). A tumor composed of atypical neoplastic, often pleomorphic cells that invade other tissues. "We discovered a new cancer gene, ribosomal protein L39 (RPL39), that is associated with therapy resistance, CSC self-renewal capacity, and lung metastases in TNBC and MpBCs8,10." (PMID 39737957, 2024). "RPL39 is associated with therapy resistance, metastasis, and cancer stem cell self-renewal of TNBCs37,38." (PMID 31704972, 2019). "In TNBC, RPL39 is important for stem cell self-renewal, therapy resistance, and lung metastases, and it promotes cancer through the inducible nitric oxide synthase signaling pathway." (PMID 37922300, 2023). "Our study provided important experimental evidence that RPL39 was an EOC-CSCs-related gene involved in cancer progression, chemoresistance and CSC formation by directly interacting with AGK in mitochondria." (PMID 35934718, 2022). "Recent studies revealed that RPL39 was involved in the development of several types of cancers." (PMID 35934718, 2022). "However, the mechanism of RPL39 involved in cancer progression remains largely unclear." (PMID 35934718, 2022).
adenocarcinoma (1 paper, 2023). A common cancer characterized by the presence of malignant glandular cells. "RPL39 was also one of the most significantly upregulated (<1 × 10−12 in our TCGA analysis of adenocarcinoma vs. normal tissue samples." (PMID 37888706, 2023).
infectious disease (1 paper, 2022). A disorder directly resulting from the presence and activity of a microbial, viral, or parasitic agent in humans. "In the case of the pre-diagnostic markers for CD4+ T cells, the upregulated genes included ribosomal proteins (e.g. RPL39, RPL37, RPS28 and RPS21) that showed enrichments in pathways related to translation and “Infectious disease”." (PMID 35371081, 2022).
RPL39 also shares sentences with these, for which no sentence is quoted: glioblastoma (1 paper); oral cavity squamous cell carcinoma (1); pulmonary arterial hypertension (1); Right ventricular hypertrophy (1); Stroke (1).